PIK3C3 (phosphatidylinositol 3-kinase catalytic subunit type 3)
Diseases named in the same sentence as PIK3C3 in open-access papers (continued):
Sharing a sentence is not in itself a finding about the gene and the disease.
tumor (continued). "The high expression levels of RAB7A, PIK3C3, ATP6AP1, ATP6V1A, CCDC22, and NPC1 were significantly associated with lower tumor purity of patients with hematologic cancer LAML, while TMPRSS2, PIK3C3, ATP6AP1, and ATP6V1A expressions were obviously correlated with higher tumor purity of KICH patients." (PMID 35082790, 2021). "Furthermore, we observed that overexpression of PIK3C3 in HCC tissues was correlated with tumor stage by analyzing clinical and pathological results in HCC samples." (PMID 32513919, 2020). "It is possible that Pik3c3 ablation caused dynamic changes in CD8+ effector T cells, NK cells, B cells, iNKT cells, and Tregs4, which together contributed to the unaltered susceptibility to tumor metastases." (PMID 32382030, 2020). "Beclin1, a tumor suppressor gene, could activate PIK3C3, which is important for ATG accumulation to start the formation of autophagosome." (PMID 29212196, 2017). "Furthermore, western blotting and RT-qPCR analysis revealed an abundance of LC3I/II, ATG7, Beclin1 and PIK3C3 in tumor samples from mice treated by juglanin." (PMID 29212196, 2017). "The transcript level of PIK3C3, a gene that acts as a coregulator of autophagy and is involved in the induction of autophagy in response to intracellular signals, was 2.704-fold higher in tumor tissues than in normal tissues." (PMID 24527027, 2014). "In some cancer types, PIK3C3 may play a tumor suppressor role, such as esophageal and oral SCCs." (PMID 34681622, 2021). "In addition, PIK3C3 could induce oncogenic transformation and enhance tumor cell proliferation and invasion through mechanisms independent of autophagy." (PMID 34681622, 2021). "In addition, PIK3C3 could induce oncogenic transformation and enhance tumor cell proliferation, growth, and invasion through mechanisms independent of autophagy." (PMID 34681622, 2021). "In addition, PIK3C3 could induce oncogenic transformation and enhance tumor cell proliferation, growth, and invasion through mechanisms independent of autophagy, while its role in cancer invasion and metastasis needs to be elucidated." (PMID 34681622, 2021). "PIK3C3 is a critical regulator of autophagy and vesicle trafficking which could maintain cell survival when modifications occur in the cellular environment and could help tumor cells resist metabolic stress and cancer treatment." (PMID 34681622, 2021). "High lactate levels in tumors act as signaling molecules, mediating PIK3C3/VPS34 Kla via TIP60 at lysines 356 and 781, which enhances autophagy and promotes tumor progression." (PMID 39897556, 2025). "The overexpression of PIK3C3 promotes the colony formation of MCF-7 cells in vitro and tumor growth in vivo." (PMID 35629298, 2022). "In our previous study, PIK3C3 was found to be poorly expressed in ESCC, acting as a tumor suppressor." (PMID 35333349, 2022). "Activation of the PIK3C3 complex by DAPK3, which phosphorylates ULK1 at Ser556, suppresses migration, invasion, and tumor growth in gastric cancer in vitro and is related to favorable patient survival outcomes." (PMID 34681622, 2021). "Overexpression of PIK3C3 promotes the colony formation of MCF-7 cells in vitro and tumor growth in vivo." (PMID 34681622, 2021). "Dual inhibition of PIK3C3 and PI3K resulted in a mild tumor regression in vivo compared with treatment with inhibitors alone." (PMID 32513919, 2020). "A positive correlation between PIK3C3 and CD133 expression was revealed in a cohort of 62 HCC tumor tissues." (PMID 32513919, 2020). "Nonetheless, the tumor data reinforce the possible involvement of cell cycle homeostasis and autophagy as PRKAA1 and PIK3C3 were the top 2 ranked genes." (PMID 28030792, 2017). "The consensus of the classifiers identifies DCLK3, MMP2, TGM3 as oncogenes and PIK3C3 and EPHA3 as tumor suppressors." (PMID 21575214, 2011).
tumor (continued). "While PIK3C3 gene expression levels decreased with the progression of the disease passing from the primary tumours to metastatic forms, PIK3CD showed the opposite trend, with higher gene expression levels in metastatic BC forms than in primary tumours." (PMID 36012280, 2022). "Moreover, we found a positive correlation between PIK3C3 and CD133 expression in a cohort of HCC tumor tissues." (PMID 32513919, 2020). "Recent studies revealed that CISD2-BCL2 complex may negatively modulate the BECN1 autophagy-initiating complex via PIK3C3 and regulate endoplasmic reticulum (ER) Ca2+ homeostasis via ER inositol 1,4,5-triphosphate receptor (ITPR/IP3R) and contributes to tumor carcinogenesis and progression in LSCC." (PMID 27007153, 2016).
cancer (76 papers, 2011 to 2026). A tumor composed of atypical neoplastic, often pleomorphic cells that invade other tissues. "In conclusion, this study provides a rational combination strategy by targeting PIK3C3 to overcome drug resistance associated with pro-survival autophagy for cancer therapy." (PMID 31514441, 2019). "Therefore, this study proofed our concept that targeting PIK3C3 to overcome drug resistance associated with pro-survival autophagy for cancer therapy." (PMID 31514441, 2019). "PI3K changes were present in cancer arrays: wt-ANXA7 inhibited the PI3K type 3 catalytic subunit p100 (PIK3C3)." (PMID 37240163, 2023). "Following a random selection of the cancer-related genes PIK3C3, PIM3, and PTEN, the researchers discovered that the cancer had progressed." (PMID 35154620, 2022). "More studies are needed to clarify the clinical and prognostic significance of PIK3C3 in different cancer types." (PMID 34681622, 2021). "ACE2, RAB7A, CCDC22, ATP6AP1, NPC1, and PIK3C3 exhibited a positive relationship with sensitivity of 18 anti-cancer drugs (P < 0.01)." (PMID 35082790, 2021). "In terms of histologic type, the PIK3C3 RNA levels were higher in colon mucinous carcinoma but lower in cervical mucinous carcinoma than in conventional-type adenocarcinoma for each cancer." (PMID 34681622, 2021). "Our findings are supported by the findings of other studies, suggesting a similar effect of inhibiting PIK3C3 in promoting anti-cancer therapy." (PMID 33946505, 2021). "Together, MPT0L145 sensitized cancer cells to targeted or chemotherapeutic agents via inhibition of PIK3C3, which perturbed the process of autophagy." (PMID 31514441, 2019). "In conclusion, the data suggest that halting pro-survival autophagy by targeting PIK3C3 with MPT0L145 significantly sensitizes cancer cells to targeted or chemotherapeutic agents, fostering rational combination strategies for cancer therapy in the future." (PMID 31514441, 2019). "Recently, autophagy has emerged as an attractive target for cancer therapy and selective PIK3C3 inhibitors were also developed as a new approach to block autophagy, such as the pyrimidinone (SAR405) and the bisaminopyrimidine (VPS34-IN1, PIK-III) compounds." (PMID 31514441, 2019). "Targeting PIK3C3 has already been proposed to improve the treatment of certain types of cancer." (PMID 40378153, 2025). "PIK3C3 has been shown to play an imperative role in the autophagy of cancer cells." (PMID 35333349, 2022). "The contradictory results may be due to the different cancer types and the experimentally manipulated mediators upstream of PIK3C3." (PMID 34681622, 2021). "Published research on PIK3C3 expression in human cancer tissues is scarce." (PMID 34681622, 2021). "Furthermore, 62.5% of SARS-CoV-2-required genes containing ACE2, TMPRSS2, ATP6AP1, ATP6V1A, and CCDC22 exhibited a significant upregulation in UCEC relative to normal tissue, while only PIK3C3 showed an obvious downregulation in this cancer." (PMID 35082790, 2021). "Validation studies involved comparison of hereditary (n = 8) and sporadic (n = 18) cases of disease with the genes of interest being PIK3C3 (on the basis of the autophagy array data) and Beclin-1, which was selected given previously demonstrated importance in other cancer types." (PMID 25487826, 2015). "By analysis of The Cancer Genome Atlas database, the mRNA level of USP1 was positively correlated with ATG14, UVRAG, and PIK3C3 (VPS34)." (PMID 39814232, 2025). "It has also been suggested that high lactate mediates PIK3C3/VPS34 emulsification and induces autophagy, thereby promoting cancer progression." (PMID 38778409, 2024). "Taken together, our data suggested that inhibiting autophagy using 36-077, a PIK3C3/VPS34 inhibitor, along with 5-FU treatment, has a profound effect on the GSK-3β/Wnt/β-catenin signaling to inhibit cancer stem cells." (PMID 33946505, 2021).
cancer (continued). "In this regard, recent studies have identified phosphatidylinositol 3-kinase (PIK3C3/VPS34 kinase), a key regulator of autophagy, as a specific and potent target for inhibiting autophagy, including in cancer cells." (PMID 33946505, 2021). "We conclude that halting pro-survival autophagy by targeting PIK3C3 with MPT0L145 significantly sensitizes cancer cells to targeted or chemotherapeutic agents, fostering rational combination strategies for cancer therapy in the future." (PMID 31514441, 2019). "In cancer cells, nuclear p-STAT3-S705 can regulate the transcription of several autophagy-related genes such as BCL2 family members (e.g., BECN1, PIK3C3, CTSB, CTSL, PIK3R1, HIF1A, and BNIP3) and microRNAs with targets of autophagy modulators." (PMID 32565533, 2019). "FOXO3 overexpression correlated with expression of the Gabarapl1, ATG12, PIK3C3, LC3, and Beclin1 genes in cancer tissues." (PMID 24527027, 2014). "KAT5/TIP60-driven lactylation of PIK3C3/VPS34 at lysine residues 356 and 781 enhances its interaction with BECN1, ATG14, and UVRAG, promoting autophagy that may contribute to cancer progression." (PMID 39979245, 2025). "Ten patients had germline mutations affecting cancer predisposition genes not typically linked to WT: CHEK2 in 4 children, and BLM, BRCA2, CDKN2A, FMN2, PIK3C3, and STK11 in one patient each." (PMID 40340749, 2025). "As further confirmation, a pharmacological approach based on PIK-III and SAR405, two specific inhibitors for PIK3C3/Vps34, a lipid kinase controlling autophagosome formation, revealed that inhibition of autophagy increases CDDP efficacy in resistant cancer cells." (PMID 40396026, 2022). "ACE2, RAB7A, PIK3C3, ATP6AP1, NPC1, and ATP6V1A had a negative association with the sensitivity of 16 anti-cancer drugs (P < 0.05)." (PMID 35082790, 2021). "Similarly, two catalytic subunits of the PI3K complex, the catalytic subunit type 3 (PIK3C3) and the catalytic subunit beta (PIK3CB), contribute to cancer growth and metastasis." (PMID 30115852, 2018). "In this pilot study, we tested our hypothesis by examining whether the mRNA expressions of three randomly selected cancer-related genes PIK3C3, PIM3, and PTEN were correlated during cancer progression and the correlation coefficients could be used for cancer diagnosis." (PMID 24818135, 2014). "These genes were not included in our original dataset either because they were not in the "Cancer Gene Census" category of COSMIC (MMP2, PIK3C3, TGM3, EPHA3) or because there was no crystal structure available (DCLK3)." (PMID 21575214, 2011).
infection (22 papers, 2011 to 2026). The state of being infected such as from the introduction of a foreign agent such as serum, vaccine, antigenic substance or organism. "The results showed that knockdown of Scarb2, Pik3c3, and Sirt2 resulted in a significant decrease of the parasite load in comparison to control cells after 48 h of infection." (PMID 37915600, 2023). "Inhibition of PIK3C3 decreased the size of infection foci formed by S. flexneri in HT-29 cells." (PMID 40378153, 2025). "Interestingly, at 48 h post-infection, a significant decrease of parasite load of 44%, 32%, and 26% was observed after knockdown of Scarb2, Pik3c3, and Sirt2, respectively." (PMID 37915600, 2023). "Interestingly, as observed for Pf13 infection, Sen91 also upregulate phosphatidylinositol 3-kinase catalytic subunit type 3, and proteins involved in “phosphatidylinositol-mediated signaling” are found enriched after infection (p-value = 9.6E-2)." (PMID 32817655, 2020). "triangularis infection-related proteins, highlighting hub genes such as AKT1, TNF, MMP9, CDK1, and PIK3C3, and enriched pathways in autophagy, immune regulation, oxidative stress responses, and kinase-mediated signaling." (PMID 41993607, 2026). "We found that PIK3C3 is required for EBOV endosomal trafficking, and inhibiting its kinase activity can significantly reduce infection, making it a promising target for antiviral therapy." (PMID 39173055, 2024). "In a chemical screen for host cell kinases required for S. flexneri dissemination, we identified seven potent compounds, including the class III phosphatidylinositol 3-phosphate kinase (PIK3C3) inhibitor VPS34-IN1, that decreased the size of the infection foci formed by S. flexneri in HT-29 cells." (PMID 40378153, 2025). "To investigate the indispensability of PIK3C3’s kinase activity in EBOV infection, we employed a selective PIK3C3 kinase inhibitor, VPS34-IN-1, and assessed its efficacy against EBOVΔVP30-EGFP infection." (PMID 39173055, 2024). "At 6 h post-infection (hpi), the enriched pathways included proteasome, ribosome, and regulation of autophagy, with the core genes of the most significantly enriched pathway in autophagy regulation (FDR = 0.2325) including ATG12, PIK3C3, GABARAPL1, ATG4C, and ATG4A." (PMID 37515115, 2023).
neurodegenerative disease (3 papers, 2021 to 2024). A disorder of the central nervous system characterized by gradual and progressive loss of neural tissue and neurologic function. "Although no somatic mutations associated with neurodegenerative diseases in the coding regions of the PIK3C3 complex subunits have been reported, several studies have implied that the reduced activity and stability of complex I could be associated with neurodegenerative diseases." (PMID 33459128, 2021).
inflammation (1 paper, 2023). Aberrant reaction of the microcirculation characterized by movement of fluid and leukocytes from the blood into extravascular tissues. "The results support the effects of ISOF via the cAMP/AQP4/SPP1/PIK3C3 axis on chronic airway inflammation, demonstrate its potential to reduce Th17 differentiation and thus the Th17/Treg balance, and provide potential targets for the treatment of this disease." (PMID 37817209, 2023).
respiratory diseases (1 paper, 2023). "Meanwhile, there have been first reports of the anti-inflammatory effects of AQP4 and PIK3C3 in respiratory diseases." (PMID 37817209, 2023). "Finally, PIK3C3 has also been found to be partially regulated by SPP1 in respiratory diseases after altering the inflammatory environment via AKT-MTOR." (PMID 37817209, 2023).
PIK3C3 also shares sentences with these, for which no sentence is quoted: glioblastoma (4 papers); non-small cell lung carcinoma (4); steatosis (4); Autoimmunity (3); cardiomyopathy (3); glioma (3); heart failure (3); Hepatic steatosis (3); hypertrophic cardiomyopathy (3); osteosarcoma (3); Sepsis (3); acute myeloid leukemia (2); Burkitt lymphoma (2); diabetes (2); gastric cancer (2); glomerulosclerosis (2); hematologic cancer (2); Huntington disease (2); Hypertension (2); intervertebral disc degeneration (2); ischemia (2); kidney disease (2); kidney failure (2); leukemia (2); lymphopenia (2); lysosomal storage disease (2); mesothelioma (2); metastatic melanoma (2); neurological disease (2); renal cell carcinoma (2).
A further 57 diseases each share a sentence with PIK3C3 in 2 papers or fewer.